5S_rRNA (5S ribosomal RNA )
Gene: Ribosomal RNA gene on chromosome 17 (37,940,704 to 37,940,790, reverse strand). Ensembl gene ENSG00000277488.
Homologues: Orthologues: mouse Gm55958 (69% identical), mouse Gm56034 (67% identical), chimpanzee 5S_rRNA (66% identical), guinea pig 5S_rRNA (54% identical). Paralogues in human: RNA5SP526 (100% identical), RNA5SP172 (66% identical), RNA5S1 (62% identical), RNA5S10 (62% identical), RNA5S11 (62% identical), RNA5S12 (62% identical), RNA5S13 (62% identical), RNA5S14 (62% identical), RNA5S15 (62% identical), RNA5S16 (62% identical), RNA5S17 (62% identical), RNA5S2 (62% identical), and 25 more.